BDNF (brain derived neurotrophic factor)
Diseases named in the same sentence as BDNF in open-access papers (continued):
Sharing a sentence is not in itself a finding about the gene and the disease.
Cognitive impairment (continued). "As BDNF mimetic, 7,8-dihydroxyflavone, a TrkB agonist, has shown neurotrophic activities and has been found to be effective in ameliorating motor and cognitive deficits." (PMID 36225186, 2022). "Although several studies have confirmed that BDNF and NGF are expressed at lower levels in peripheral blood of patients with SCZ, MDD, and BD, their association with cognitive impairment remains controversial." (PMID 36406755, 2022). "Several studies have looked at the serum levels of BDNF in cognitive impairment and AD, with results still controversial." (PMID 36498925, 2022). "Several products of activated microglia, such as inteleukin-1, nitric oxide and prostaglandins have been shown to suppress the expression of BDNF and are related to depressive symptoms, cognitive disorders and fatigue." (PMID 35344113, 2022). "A recent cross-sectional study that used BACS as a measurement instrument to observe the relationship between cognitive impairment in SCZ and peripheral BDNF levels, found an association between them." (PMID 36552127, 2022). "The decline of BDNF and TrkB further aggravates neurological damage and eventually leads to cognitive impairment." (PMID 36683819, 2022). "This review explores the possible role of BDNF-mediated cognitive impairment in hypothyroid patients." (PMID 35506116, 2022). "Cognitive impairment is a core symptom of SCZ and a number of studies have found an association between neurocognitive deficits and peripheral BDNF levels." (PMID 36281033, 2022). "In a mouse model, trigonelline protects against lipopolysaccharide-mediated cognitive impairment by reducing OS, inhibiting proinflammatory cytokine levels, and restoring brain-derived neurotrophic factor (BDNF) levels." (PMID 36632095, 2022). "A previous study had demonstrated that the C57BL/6 mice exposed to isoflurane during aging exhibited cognitive deficits, which were accompanied by inhibition of the BDNF pathway and downregulation of synaptic plasticity markers in the hippocampus." (PMID 35910680, 2022). "Scopolamine−induced memory loss and cognitive impairment were alleviated by PPM ethanol extract, which regulates cholinergic function, brain−derived neurotrophic factor (BDNF) and neuronal death." (PMID 36557335, 2022). "BDNF in the male and female groups first decreased and then increased significantly with cognitive impairment (P < 0.001)." (PMID 36425322, 2022). "The hippocampal levels of BDNF have been reported to be downregulated under conditions of cognitive impairment induced by prenatal restraint stress, perinatal ethanol exposure, and chronic social isolation stress in rodents." (PMID 36570704, 2022). "Dietary zinc supplementation treatment in 3xTg-AD mice has been shown to increase Brain-derived neurotrophic factor (BDNF) levels and prevent cognitive deficits and mitochondrial dysfunction." (PMID 35197970, 2022). "Brain-derived neurotrophic factor (BDNF) and Synaptotagmin-1 (Syt-1) are two important synaptic plasticity markers, which have been experimentally confirmed to be associated with cognitive impairment induced by early life stress." (PMID 35910680, 2022). "BDNF and proBDNF protein levels were decreased in the human parietal cortex of subjects with mild cognitive impairment (MCI) and AD patients." (PMID 35887075, 2022). "The entry of circulating heparan sulfate fragments into the hippocampus sequesters BDNF, impairs LTP, and causes septic cognitive impairment." (PMID 35711904, 2022). "Severe hypothyroidism in the neonatal period leads to developmental and cognitive impairments due to reduced mRNA and protein expression of BDNF in the hippocampus, cerebral cortex and cerebellum." (PMID 35506116, 2022). "Brain-derived neurotrophic factor (BDNF) has been proposed to be a biomarker of cognitive impairment in these disorders as it plays a critical role in neuroplasticity and proposed to mediate some of the psychotropic effects of medication." (PMID 35686181, 2022).
Cognitive impairment (continued). "Consistent with our previous work, we found a decreased ratio of pCREB/CREB and BDNF expression in the hippocampus in rats with TN and cognitive deficits." (PMID 36478990, 2022). "A recent study found that co-treatment with MLA promoted the reduction of BDNF in the hippocampus and worsened Aβ-induced cognitive impairment, suggesting a determinant role of α7nAChR in BDNF expression and memory recovery in AD." (PMID 35721159, 2022). "Overall, enhancement of BDNF expression is proposed as a key mechanism in neuroprotection and rescue of cognitive impairment via PAC1R." (PMID 36403002, 2022). "This study also found that 1% taurine treatment can significantly improve VOCs-induced cognitive impairment in young rats by upregulating the protein expression of BDNF." (PMID 36187803, 2022). "Fisetin attenuated histological injury, malondialdehyde levels, inflammasome pathway activation, apoptosis, as well as increased BDNF expression, reduced astrocyte, microglial activation, and cognitive deficits." (PMID 35740470, 2022). "We and other researchers have reported that dysregulation of BDNF/TrkB signaling leads to cognitive impairment after surgery and anesthesia, and BDNF upregulation by neuroprotective agents rescued this deficit." (PMID 35721159, 2022). "It has been proposed that HFD decreases the brain-derived neurotrophic factor (BDNF) involved in cognitive impairment, probably by oxidative stress and ROS formation." (PMID 36290695, 2022). "In patients with HAND, studies have shown that decreased BDNF levels correlate with cognitive defects." (PMID 35418836, 2022). "The cognitive deficits coincided with reduced neurogenesis and brain-derived neurotrophic factor (BDNF) in the hippocampus." (PMID 35562883, 2022). "Recent studies have shown that a diet rich in simple sugars and saturated fatty acids reduces the expression of brain-derived neurotrophic factor (BDNF), where a decrease in its levels has been associated with metabolic syndrome and cognitive impairment." (PMID 35883542, 2022). "Lactobacillus johnsonii CJLJ103 mitigated scopolamine-induced cognitive impairment in mice by increasing NF-κB-involved BDNF expression." (PMID 35889931, 2022). "Our study demonstrated that MSD-induced offspring exhibited anxiety-like behavior, cognitive impairment, and BDNF and Syt-1 expression." (PMID 35910680, 2022). "Resveratrol treatment upregulated the decreased levels of pCREB and BDNF protein in the neurons and astrocytes of TN rats and improved TN-induced cognitive deficits." (PMID 36478990, 2022). "In a rat model of AD, direct intervention in the hippocampus with the 42 amino acid form of amyloid β (Aβ1–42) resulted in cognitive impairment by suppressing PGC1α/FNDC5/BDNF signaling." (PMID 35764750, 2022). "BDNF-pathway has been indicated as a mediator between neuroinflammation and cognitive impairment, and also IL-1β played a crucial role in regulation of BDNF levels." (PMID 35370607, 2022). "Decreased hippocampal BDNF expression, with significant neuronal damage and cognitive impairment, was observed in a vascular dementia rat model." (PMID 35743271, 2022). "The activation of the BDNF/TrkB signaling pathway has been demonstrated to regulate brain inflammation, relieve apoptosis, and protect against cognitive disorder." (PMID 35615581, 2022). "Regarding this, the aim of this study is to analyze the effect of a multicomponent exercise program with stimulation on fitness, cognitive function, plasmatic lipid profile, oxidative stress, and BDNF of elderlies with mild cognitive impairment." (PMID 36092805, 2022). "Analysis of CSF and serum of patients with mild cognitive impairment and dementia of AD type, as well as the hippocampus of an AD mice model, indicated that miR-613 downregulates the expression of BDNF through directly targeting 3′ UTR." (PMID 35916975, 2022).
Cognitive impairment (continued). "Changes in the BDNF expression have been shown to inversely correspond to increased H3K9me3 in a postoperative model of cognitive impairment or downregulation in mice with inhibited activity of SUV39H1." (PMID 35042834, 2022). "Juvenile offspring of poly (I:C)-treated pregnant animals displayed cognitive deficits and a significant decrease in BDNF-TrkB (tyrosine kinase receptor) signaling in mouse prefrontal cortex." (PMID 36438556, 2022). "Interestingly, BDNF has been tightly linked with cognitive function and studies show that there are lower levels of BDNF in the brains of MS patients, which is hypothesized to be correlated to MS-related cognitive deficits." (PMID 35563884, 2022). "The results of this study demonstrate the necessity of BDNF activity in the IL for the beneficial effects of extinction on restoring stress-induced cognitive deficits in both male and female rats." (PMID 34497360, 2022). "BDNF first decreased and then increased with cognitive impairment in the ApoE4-negative group (P < 0.05)." (PMID 36425322, 2022). "Pearson and Spearman correlation analysis examined the correlation between BDNF and cognitive impairment, and linear regression analysis examined the comprehensive effects of diagnosis, gender, age, education, and sample source on BDNF." (PMID 36425322, 2022). "It clearly suggests that decreased BDNF-TrkB signaling is a key pathway involved in the cognitive deficits of MIA offspring." (PMID 36438556, 2022). "This mutation can cause a misfolding of the protein, with an impact on binding to TrkB receptor and on BDNF functions, mainly in the hippocampus and on cognitive impairment in older subjects." (PMID 36498925, 2022). "Experiments have demonstrated an inhibitory effect of PTX on BDNF, which ultimately changes synaptic plasticity and leads to cognitive impairment." (PMID 35944285, 2022). "Brain-derived neurotrophic factor (BDNF) is well known as a beneficial marker for cognition; its deficit contributes to cognitive disorders and results in APP fragmentation." (PMID 36040555, 2022). "We found that BDNF is a moderating factor in the relationship between the severity of cognitive impairment and the dysfunction of DPMS." (PMID 36248031, 2022). "Our previous study also demonstrated that the hippocampal CREB/BDNF pathway was downregulated in TN-induced cognitive deficits." (PMID 36478990, 2022). "The addition of endogenous GQ1b was shown to ameliorate cognitive impairments via BDNF in another neurodegenerative disease, Alzheimer’s (in a triple transgenic mouse model), and GQ1b increased BDNF expression more effectively than GM1a." (PMID 34757540, 2022). "BDNF is a neurotrophic factor that is essential for brain homeostasis (i.e., neurogenesis, neuronal survival, and cognitive impairment from various insults such as ROS) in the hippocampus." (PMID 34299412, 2021). "The effect of cognitive impairment on plasma levels of BDNF, 3-NT, IGF-1, IGF-2 and IGFBP-3 was evaluated using Student’s t test." (PMID 34341419, 2021). "Decreased peripheral BDNF levels have been widely demonstrated in both medicated and drug-naive first-episode patients with schizophrenia, potentially contributing to their cognitive impairments, revealed by recent meta-analyses." (PMID 34239458, 2021). "Physical exercise, which increases BDNF levels in the hippocampus and neocortex, reduced neuroinflammation and cognitive deficits in a model of stroke." (PMID 32676979, 2021). "To summarize, reduced BDNF levels have long been suggested as a marker for neuroplastic and cognitive deficits in schizophrenia." (PMID 33558459, 2021). "In this study, as a first step to explore the possible involvement of brain inflammation in BDNF induced rescue of cognitive deficits in AD11 mice, we have assessed the presence of microgliosis in the hippocampus." (PMID 32676979, 2021).
Cognitive impairment (continued). "Although its early delivery appears a preventive approach, the BDNF potential in rescuing already existing cognitive deficits still remains an open question." (PMID 32676979, 2021). "Studies indicated that the downregulation of neurotrophic factors, especially BDNF, plays an important role in cognitive impairment and neurodegeneration." (PMID 34354558, 2021). "In patients with chronic schizophrenia, cognitive deficits have been related to various factors, including the severity of psychotic symptoms, age, medication, as well as BDNF levels." (PMID 34220575, 2021). "Consistently, data has revealed an increase in the level of mature BDNF and a reduction in truncated BDNF in patients with schizophrenia with cognitive deficits." (PMID 33767621, 2021). "Combined prophylactic and therapeutic treatment with rhANP-mediated attenuation of neuroinflammation and cognitive impairment was accompanied by a up-regulation of p-TrkB and BDNF in the hippocampus." (PMID 34949194, 2021). "BDNF is thought to be a key regulator of learning and memory, which is involved in the pathogenesis of schizophrenia and is especially related to cognitive deficits." (PMID 33767621, 2021). "In patients with AD, the severity of cognitive impairment is related to BDNF and amyloid beta (Aβ1–42) plasma levels in serum." (PMID 34299040, 2021). "FBXO10 overexpression or RAGE knockdown inhibited proinflammatory cytokine release, promoted BDNF expression, mitigated the depressive‐like and cognitive impairment behaviors, and inhibited the polarization of M1 microglia." (PMID 34492157, 2021). "Specifically, cognitive impairment can be induced by decreased hippocampal brain-derived neurotrophic factor (BDNF) expression." (PMID 33920851, 2021). "A decrease in BDNF expression is evident early in the progression of AD, being already apparent in subjects with Mild Cognitive Impairment or mild AD." (PMID 32676979, 2021). "Radiation-induced up-regulation of miR-34a-5p in the small intestine and peripheral blood down-regulated hippocampal BDNF, leading to the cognitive impairment." (PMID 34572124, 2021). "Nevertheless, our study demonstrated that acute early life stress, in the form of 24 h maternal separation, induced long-term morphological changes in the prefrontal GABAergic system and microglia along with upregulation of BDNF and a mild cognitive deficit." (PMID 34819843, 2021). "Residual schizophrenia, and its most known manifestation (cognitive impairment), is characterized by a typical biochemical decrease in BDNF and TNF-α, and at the same time an increase in IL-2, IL-6, and IL-8." (PMID 34434228, 2021). "In vivo, GO@Dau effectively improved the cognitive impairment and pathological damage in AD mice, up-regulated the expression of BDNF, and inhibited the activation of microglia and astrocytes induced by Aβ1-42." (PMID 33729067, 2021). "FBXO10 overexpression or RAGE knockdown inhibited proinflammatory cytokine release, promoted BDNF expression, mitigated the depressive‐like and cognitive impairment behaviors, and affected the polarization of microglia induced by CUS exposure." (PMID 34492157, 2021). "In four studies concerning people with cognitive impairments, one showed an increase in BDNF concentration levels after a PA intervention, two studies presented no change whatsoever, and one displayed contradictory results." (PMID 34445512, 2021). "For instance, BDNF serum levels were significantly reduced in almost all cognitively-impaired groups, such as mild cognitive impairment, Alzheimer's disease, and Parkinson's disease." (PMID 34239458, 2021). "The model of the antibiotic-induced gut dysbiosis was also explored, as it would cause changes in the expression of TJs, cytokines, brain-derived neurotrophic factor (BDNF) and 5-HT transporter, eventually resulting in cognitive impairment." (PMID 34440503, 2021).
Cognitive impairment (continued). "BDNF Met66 carriers show increased risks of developing cognitive impairment and mood disorders as a result of impaired BDNF pro-protein sorting and secretion." (PMID 34238925, 2021). "Moreover, alterations in BDNF expression and BDNF/TrkB signaling pathway might induce synapse loss and the consequent cognitive dysfunction, while early downregulation of BDNF in AD was associated with the severity of cognitive impairments." (PMID 34195199, 2021). "In conclusion, SK inhibited hippocampal neuronal apoptosis to protect against CCH-induced injury by regulating the PTEN/Akt/CREB/BDNF signaling pathway, consequently improving cognitive impairment." (PMID 34211568, 2021). "It is thought that BDNF/TrkB contribute to not only cognitive impairment (including learning deficits and memory impairment) but also mental disorders (including schizophrenia, mood disorders, intellectual disability, and autism)." (PMID 34299040, 2021). "Future development of diagnosis and therapy to correct cognitive deficits through BDNF and other neuroplasticity mechanisms should consider the micro-RNA-BDNF mechanism." (PMID 33558459, 2021). "Further studies are warranted to elucidate the dependence of AT2R stimulation on BDNF secretion, as well as the role of acute C21 administration on Th17 cells and cognitive impairment in female animals." (PMID 33572986, 2021). "Reduced expression of BDNF in the hippocampus and parietal, entorhinal and frontal cortices results in noticeably reduced plasticity and cognitive impairment, which are correlated with progression of neurodegeneration and dementia." (PMID 34206011, 2021). "A growing body of evidence suggests that surgical trauma and anesthesia inhibit BDNF expression, resulting in cognitive impairment." (PMID 34168535, 2021). "We aimed to investigate the roles of brain-derived neurotrophic factor (BDNF) and the Val66Met polymorphism in mild cognitive impairment (MCI) in patients with type 2 diabetes mellitus (T2DM)." (PMID 35111074, 2021). "This reduction in BDNF levels has also been observed in other pathologies related to cognitive deficit." (PMID 34576069, 2021). "With each episode, lower BDNF levels result in more significant cognitive impairment and reduced functionality, further reducing the chances of returning to euthymia." (PMID 33732117, 2021). "The decrease in BDNF expression appears to correlate with the degree of cognitive deficits in humans." (PMID 34199883, 2021). "HDACi induced an increase in levels of BDNF and AMPARs, which protect against hippocampal atrophy and cognitive impairment following CCH." (PMID 34216182, 2021). "Previous literature has indicated that lower serum BDNF levels were related to the development of mild cognitive impairment, AD and higher brain BDNF levels are related to slower rates of cognitive decline." (PMID 34408648, 2021). "Infusion of BDNF protein into the hippocampus of rat AD model (ventricular injection of Aβ), or daily i.p. injection of a BDNF-mimicking peptide was able to halt neuronal death and ameliorated cognitive impairment 47-49." (PMID 32550908, 2020). "The late cognitive impairments involving memorization process lead us to evaluate brain levels of two major central neurotrophic factors: brain derived neurotrophic factor (BDNF) and nerve growth factor (NGF)." (PMID 32066806, 2020). "For instance, the reduction of BDNF is regarded to partly lead to cognitive impairment in type 2 diabetes mellitus (T2DM)." (PMID 33029194, 2020). "Brain-derived neurotrophic factor (BDNF), a key mediator of cognitive impairment in Alzheimer’s dementia." (PMID 32962184, 2020). "We found that EE exposure improved cognitive impairment in the offspring, and increased histone acetylation and BDNF expression in the hippocampus." (PMID 32813852, 2020).